PTGS2 (prostaglandin-endoperoxide synthase 2)
Diseases named in the same sentence as PTGS2 in open-access papers (continued):
Sharing a sentence is not in itself a finding about the gene and the disease.
cardiac hypertrophy (8 papers, 2021 to 2026). "To investigate the activation of ferroptosis in cardiac hypertrophy, we analysed several ferroptosis‐associated markers, including malondialdehyde (MDA), prostaglandin‐endoperoxide synthase 2 (Ptgs2), Gpx4, and mitochondrial morphology." (PMID 40000392, 2025). "Ptgs2, malondialdehyde, and ROS levels substantially increase Ang II-induced cardiac hypertrophy; however, ferroptosis blocker xCT attenuates these changes, inhibiting cardiac hypertrophy." (PMID 37731525, 2023). "Gene–disease association information were as follows: HIF1A is associated with heart failure and cardiac hypertrophy; IL6 is associated with heart failure and cardiomyopathy; PTGS2 is associated with aortic aneurysms, heart failure, cardiac arrhythmias, cardiomyopathy, and CVD." (PMID 37283588, 2023). "Moreover, TQ inhibits cardiomyocyte ferroptosis and apoptosis by downregulating PTGS2, Bax, and upregulating GPX4, Bcl-2, thereby alleviating cardiac hypertrophy and dysfunction." (PMID 41614426, 2026).
esophageal squamous cell carcinoma (8 papers, 2009 to 2025). Esophageal squamous cell carcinoma (ESCC) is a type of esophageal carcinoma (EC) that can affect any part of the esophagus, but is usually located in the upper or middle third. "In another study, the PTGS2 expression modulated esophageal squamous cell carcinoma radiosensitivity by inhibiting ferroptosis." (PMID 35359830, 2022).
gastritis (8 papers, 2015 to 2024). Inflammation of the stomach. "In conclusion, the potential mechanism of Weibing Formula 1 in treating gastritis has the multicomponent, multitarget, and multiway characteristics, and PTGS2, NOS2, EGFR, MMP9, CXCL2, CXCL8, and IL-10 may be the important direct targets of Weibing Formula 1 in gastritis treatment." (PMID 34471638, 2021). "In addition, PTGS2, TRL4, MMP9, JAK1, EGFR, CYP2C19, and PTGS1 were identified as crucial anti-gastritis target genes in C. cassia." (PMID 35336597, 2022). "PTGS2, NOS2, EGFR, MMP9, CXCL2, CXCL8, and IL-10 may be the important direct targets of Weibing Formula 1 in gastritis treatment." (PMID 34471638, 2021).
lymph node metastasis (8 papers, 2013 to 2024). "A recent study revealed the prognostic significance of PTGS2 (COX2) mRNA expression; high levels of PTGS2 mRNA are associated with lymph node metastasis in NPC patients." (PMID 23777485, 2013). "Elevated PTGS2 and VEGF signalling pathway expression in OSCC correlates with a higher likelihood of lymph node metastasis." (PMID 38426619, 2024). "For validation at the experimental level, the expression of PTGS2, MET, and ICAM1 was analyzed via immunohistochemical staining of pathological sections from the lymph node metastasis and non-metastasis groups." (PMID 37274228, 2023).
type 1 diabetes (8 papers, 2013 to 2025). "Clinical research demonstrated that patients with type 1 diabetes exhibit increased expression of PTGS2 in the peripheral blood mononuclear cells (PBMCs), which leads to dysfunction of PBMCs40." (PMID 26813334, 2016). "Prolonged CSF2 expression, high GM-CSF production, and GM-CSF activation of PTGS2 gene expression all are seen in type 1 diabetes (T1D) monocytes." (PMID 24204704, 2013).
colonic adenomas (7 papers, 2017 to 2023). "As in our CRC cohort, PTGS2-positive stromal populations with a luminal distribution were previously observed in colon adenomas: Chapple and Bamba independently attributed PTGS2 positivity to macrophages, according to cell morphology or CD68 expression." (PMID 32168749, 2020). "Prostaglandins E2 (PGE2) produced by PTGS2 and PTGES has been reported to have a vital role in CRC tumorigensis and celecoxib, a selective inhibitor of PTGS2, reduced colon adenoma in ApcMin/+ mice by blocking PGE2 synthesis." (PMID 37041160, 2023).
dermatitis (7 papers, 2017 to 2025). An inflammatory process affecting the skin. "PTGS2 is widely used as an inflammatory marker of skin inflammation and is related to the pathogenesis of skin injury." (PMID 35372072, 2022). "Increased PTGS2 expression has also been observed in the suprabasal epidermal region of guinea pig skin in response to iodide and in murine epidermis in retinol- or benzalkonium chloride–induced dermatitis." (PMID 34909715, 2021).
edema (7 papers, 2018 to 2025). An abnormal accumulation of fluid beneath the skin, or in one or more cavities of the body. "PTGS2 had increased transcription for both hydrostatic and ARDS pulmonary edema fluid (~20-fold and 1000-fold increase, p values 0.002 and 0.02, respectively), but TSG-6 transcription was induced solely by ARDS pulmonary edema fluid (6-fold increase, p value 0.02)." (PMID 33021986, 2020).
gastric adenocarcinoma (7 papers, 2010 to 2025). "Expression of PTGS2 (COX2) was measured in AGS cells and in primary gastric adenocarcinoma tissues." (PMID 21194482, 2010).
heart failure (7 papers, 2005 to 2023). Inability of the heart to pump blood at an adequate rate to meet tissue metabolic requirements. "To identify if the Cre recombinase promoted cardiac fibrosis and heart failure related to an underlying ferroptotic mechanism, we used real-time quantitative PCR to detect the mRNA expression level of PTGS2 gene, a putative molecular marker of ferroptosis." (PMID 36834504, 2023). "Inclusively, the expression patterns of the most proteins (MMP-2, Col1a1, Col3a1, N-Cadherin, β-Catenin, CnA, RyR, SERCA2 and PTGS2) in human heart failure are consistent with the discoveries above in the Cre recombinase-induced cardiotoxicity model." (PMID 36834504, 2023).
memory impairment (7 papers, 2017 to 2022). "Similarly, lipid peroxidation and gene markers (GPX4, SLC7A11, SLC1A5, and PTGS2) dysregulation of ferroptosis were discovered in the CCI-induced memory impairment model." (PMID 35547819, 2022). "We also discovered that ATF3 was considerably overexpressed in the hippocampal CA1 area, and gene markers of ferroptosis, such as GPX4, SLC7A11, SLC1A5, and PTGS2, were dysregulated in the CCI-induced memory impairment paradigm." (PMID 35547819, 2022).
osteoporosis (7 papers, 2013 to 2026). A condition of reduced bone mass, with decreased cortical thickness and a decrease in the number and size of the trabeculae of cancellous bone (but normal chemical composition), resulting in increased fracture incidence. "PTGS2 is an inflammatory mediator involved in bone fracture healing, and inhibition of PTGS2 is associated with suppression of bone absorption and osteoporosis." (PMID 27331400, 2016). "Therefore, dysregulation of the TNFα-Ptgs2-Bcl2 pathway might be a cause of the bone loss and osteoporosis observed in SMA patients." (PMID 27331400, 2016). "Based on network pharmacology, core targets (PTGS1 and PTGS2) and key ingredients (kaempferol, beta-sitosterol, stigmasterol, fumarine and frutinone A) that might play pivotal roles in treating osteoporosis were screened out." (PMID 37464262, 2023). "Therefore, PTGS1 and PTGS2 might be involved in the development and treatment of osteoporosis, and our results of network pharmacology were in line with previous studies." (PMID 37464262, 2023). "PTGS2, also known as COX-2 (Cyclooxygenase-2), is intimately involved in bone metabolism and has significant implications for osteoporosis in postmenopausal women." (PMID 40699728, 2025). "Additionally, PPARG, PTGS2, IL6, STAT3, and JUN have been reported to play important roles in the development of osteoporosis." (PMID 40299567, 2025).
periodontal disease (7 papers, 2015 to 2025). "In this study, we focused on exploring the key crosstalk genes shared by AAA and periodontal disease (IL1B, PTGS2, and SELL) through comprehensive bioinformatics methods and validated using an external independent dataset." (PMID 40857330, 2025).
preeclampsia (7 papers, 2012 to 2025). Preeclampsia is a hypertensive disorder of pregnancy that is characterized by new-onset hypertension with proteinuria presenting after 20 weeks of gestation, and depending on mild or severe forms may initially present with severe headache, visual disturbances, and hyperreflexia. "PTGS2 knockdown reversed the facilitating effect of LPS on trophoblast invasion and inflammation in preeclampsia." (PMID 40380246, 2025). "This manifests in clinical preeclampsia in humans and leads to the activation of RAS and the placental inflammatory mediators Hif1a and Ptgs2." (PMID 34959804, 2021).
rectal cancer (7 papers, 2012 to 2023). A primary or metastatic malignant neoplasm that affects the rectum. "Copy number increase of EFNA1 (1q22), PTGS2 (1q31.1), KDM5B (1q32.1), ESRRG (1q41), KIFC1 (6p21.32), PBX2 (6p21.32) and SOX4 (6p22.3) were only detected in rectal cancer in array CGH." (PMID 23158542, 2012). "A SNP in PTGS2 (−765G>C; rs20417) resulting in decreased COX2 expression has been strongly associated with the risk of developing rectal cancer but not colon cancer." (PMID 29193751, 2018).
acute pancreatitis (6 papers, 2017 to 2025). An acute inflammatory process that leads to necrosis of the pancreatic parenchyma. "In summary, using network pharmacology methods and molecular docking techniques, this study identified quercetin and other active components in Salvia miltiorrhiza to be effective against acute pancreatitis by targeting PTGS2, NCOA1, and other key genes." (PMID 34868345, 2021).
E. coli infection (6 papers, 2020 to 2025). "Transcriptomic analysis revealed that the most significant changes in gene expression following E. coli infection in BMDMs were associated with the “inflammatory response,” with a notable increase in cytokines and PTGS2 expression." (PMID 40874199, 2025). "The expression of PTGS2, a marker of ferroptosis, markedly increased in endometrial tissue after E. coli infection." (PMID 41413615, 2025). "In accordance with the in vitro findings, PTGS2 expression in BEECs increased as the duration of E. coli infection increased, whereas GPX4 expression significantly increased at 1 h post-infection, and SLC7A11, GPX4, and FTH1 expression significantly decreased at 5 h post-infection." (PMID 41413615, 2025). "However, neutrophilic PTGS2 expression and IL6 expression in the amnion is differentially induced by E. coli infection." (PMID 34495952, 2021).
encephalitis (6 papers, 2015 to 2025). An acute inflammatory process affecting the brain parenchyma. "Moreover, HSV-1-induced ferroptosis played an important role in the development of viral encephalitis in mice, and the upregulation of PTGS2 and PGE2 activated by ferroptosis contributes to encephalitis." (PMID 36507835, 2023). "HSV-1 ferroptosis-activated upregulation of PTGS2 and PGE2 contributes to viral encephalitis." (PMID 36507835, 2023).
hyperuricemia (6 papers, 2018 to 2026). An abnormally high level of uric acid. "The core targets of Plantaginis Herba for the treatment of hyperuricemia were AKT1, mitogen-activated protein kinase 3 (MAPK3), MAPK1, tumor necrosis factor (TNF), prostaglandin-endoperoxide synthase 2 (PTGS2), sirtuin 1 (SIRT1), estrogen receptor 1 (ESR1), and androgen receptor (AR)." (PMID 33897800, 2021).
injury (6 papers, 2021 to 2024). Damage inflicted on the body as the direct or indirect result of an external force, with or without disruption of structural continuity. "In acute lung injury, the impact of NLRP3 inflammasome could be reduced by inhibiting the expression of PTGS2." (PMID 37920214, 2023).
nasal polyps (6 papers, 2014 to 2024). "For example, a stimulatory rather than inhibitory effect of glucocorticoids on expression of prostaglandin-endoperoxide synthase 2 (PTGS2), the rate-limiting enzyme in prostaglandin production, has been shown in amnion fibroblasts, placental cytotrophoblasts, cardiomyocytes, and nasal polyps." (PMID 24848801, 2014). "Additionally, in nasal polyps, PTGS2 is enriched in the MCTC cluster, which we could not observe in HLMC." (PMID 37063885, 2023).
pancreatic ductal adenocarcinoma (6 papers, 2013 to 2022). An infiltrating adenocarcinoma that arises from the epithelial cells of the pancreas. "LncRNA prostaglandin-endoperoxide synthase 2 (PTGS2) antisense NF-κB1 complex-mediated expression regulator RNA (PACERR) is an important contributor to the polarization of TAMs in pancreatic ductal adenocarcinoma (PDAC)." (PMID 36263199, 2022).
Peptic ulcer (6 papers, 2009 to 2025). The term peptic ulcer refers to acid peptic injury of the digestive tract, resulting in mucosal break reaching the submucosa. "In our analyses, both PTGS1 and PTGS2 proteins are linked to Peptic ulcer and Peptic ulcer haemorrhage ADRs with significant q-values." (PMID 34679164, 2021). "The PPI network was constructed for the peptic ulcer genes, the constructed network to show the interactions between peptic ulcer targets proved that the following genes have the higher node degrees; AKT1, TNF, SRC, EGFR, ESR1, PTGS2, MMP9." (PMID 38728332, 2024).
polyp (6 papers, 2015 to 2024). A usually exophytic mass attached to the underlying tissue by a broad base or a thin stalk. "IL1B, IL8 and PTGS2 were significantly higher in stool from cancer patients compared to the polyp and control group (p < 0.05)." (PMID 39523395, 2024). "Decreased expression of Ptgs2 in colonic polyps and non-polyp tissues was also observed in Clec7a−/− mice under SPF conditions, and PGE2 concentration in colonic tissue homogenate was decreased in these mice." (PMID 36932082, 2023). "Decreased Ptgs2 expression in intestinal polyps was also observed in ApcMin/+Clec7a−/− mice, and its expression was only detectable in CD45+ leukocytes, but not in EpCAM+ epithelial cells, in both polyps and non-polyp tissues." (PMID 36932082, 2023).
renal fibrosis (6 papers, 2016 to 2025). A final common manifestation of a wide variety of chronic kidney diseases characterized by glomerulosclerosis and tubulointerstitial fibrosis. "Together, these results indicated that HCQ probably inhibits the activity of PTGS2 by binding to it, thereby alleviating renal fibrosis and delaying the progression of IgAN." (PMID 40418206, 2025). "Clinical data and in vitro experiments suggested that HCQ probably exerted therapeutic effects by inhibiting the function of PTGS2, thereby alleviating renal fibrosis." (PMID 40418206, 2025). "In doxorubicin induced-renal fibrosis animals, the non-heme iron levels, and the mRNA of renal prostaglandin–endoperoxide synthase 2 (PTGS2), a putative marker of ferroptosis, were increased in kidneys, which suggested a possible role of ferroptosis in renal fibrosis." (PMID 35050181, 2022).
thyroid cancer (6 papers, 2010 to 2023). "It has been demonstrated that PTGS2 gene is detected in a large part of human thyroid cancer, which highlights the possibility of inhibiting tumor growth through COX-2 inhibition." (PMID 37898675, 2023). "Analysis of publicly available datasets showed co-expression of PTGS2 and M2 markers in a consistent fraction of human thyroid cancer tissues." (PMID 31113465, 2019). "Taken together, these data show co-expression of PTGS2 and M2 markers in a significant fraction of human thyroid cancer tissues, supporting our in vitro findings." (PMID 31113465, 2019).
B cell lymphoma (5 papers, 2022 to 2024). "(2023) demonstrated a consistent correlation between PTGS2 upregulation and chromosome 17p deletions in human B-cell lymphomas, linking arachidonate metabolism as a new susceptibility factor for lymphoma." (PMID 39450252, 2024). "In a B cell lymphoma model, KD of Alox8 or Alox8 in combination with cyclooxygenase 2 (Ptgs2) were injected into the tail vein of sublethally irradiated mice." (PMID 38637408, 2024).
cardiomyopathy (5 papers, 2012 to 2023). A disease of the heart muscle or myocardium proper. "Although nonsteroidal anti-inflammatory drugs (NSAIDs), which inhibit PTGS2, are usually successful in suppressing preterm labor or prolonging pregnancy in animal and human studies, the NSAIDs have adverse effects on fetal physiology and development, including renal defects and cardiomyopathies." (PMID 26229240, 2015).
endometritis (5 papers, 2009 to 2025). An acute or chronic, usually bacterial infectious process affecting the endometrium. "The uterine infection caused a massive (∼90-fold) upregulation of the prostaglandin-endoperoxide synthase 2/cyclooxygenase-2 gene (PTGS2)." (PMID 19956711, 2009). "The hypothesis of increased expression of interleukins and PTGS2 in cows with endometritis caused by a bacterial infection is supported by in vitro studies of endometrial cells co-cultured with pathogenic bacteria." (PMID 25803719, 2015). "Endometritis in pigs provoked by E. coli changed the contents of PGF2α, elevated the PTGS-2 and PG 9-ketoreductase/carbonyl reductase (CBR1) expression and reduced the expression of PGFS." (PMID 40565335, 2025). "During clinical endometritis in cows, a rise in the mRNA expression of PG-endoperoxidase synthase-2 (PTGS-2) was noted." (PMID 40565335, 2025). "It has been found previously that mRNA PTGS2 is highly expressed only in the clinical form of endometritis." (PMID 33478124, 2021). "The observed result might indicate that in the late stage of the uterus involution or under pathological status (i.e., subclinical endometritis), the endometrial expression pattern of PTGS2 is different than during the physiological estrus cycle." (PMID 33478124, 2021). "We report that endometritis led to the increase in PGE2 secretion by noradrenaline, which coincides with the augmented PTGS-2 and mPTGES-1 protein expression." (PMID 36982930, 2023).
glaucoma (5 papers, 2012 to 2025). Increased pressure in the eyeball due to obstruction of the outflow of aqueous humor. "For each of the 4 clusters, notable genes associated with glaucoma, neuroinflammation, or reactive astrocytes were: Cluster 1 (Nrf2, Hspb1, S100β), Cluster 2 (Ptgs2, Clcf1), and Cluster 4 (C2, Tlr4, Lcn2, H2-T23, Thbs1, Il6ra)." (PMID 37759301, 2023). "Moreover, the genes NOS1 and PTGS2 have been associated with glaucoma." (PMID 23028713, 2012). "Several mRNAs, such as BLM, Ubc, Ptgs2, and Jun, have been shown to be involved in cataract development; however, the role of differential mRNA expression in cataract progression in glaucoma patients remains unclear." (PMID 37131205, 2023).
hyperlipidemia (5 papers, 2021 to 2025). "The results from the PPI analysis showed that the targets for YCWL relating to the treatment of hyperlipidemia mainly involved AKT1, IL6, VEGFA, and PTGS2." (PMID 34746316, 2021).
intestinal tumors (5 papers, 2017 to 2023). "It has been found that PTGS2 play a key role in the development of ovarian and intestinal tumors." (PMID 35933696, 2022).
lymphoma (5 papers, 2014 to 2024). A malignant (clonal) proliferation of B- lymphocytes or T- lymphocytes which involves the lymph nodes, bone marrow and/or extranodal sites. "Loss of Alox8 specifically induced Ptgs2 expression, inhibiting which would prevent Alox8-deficient B progenitor cells transformed into lymphoma, and suppress Alox8-deficient lymphoma cell growth." (PMID 36750552, 2023). "The cyclooxygenase pathway was upregulated in both Alox8 deficient and 11B3-deleted mouse lymphoma cells, indicated by increased levels of Ptgs2 expression and its product PGE2." (PMID 36750552, 2023). "Consistent with the increased levels of the cyclooxygenase pathway metabolites, we found that Ptgs2 but not Ptgs1 gene expression was dramatically induced up to 250-fold in Alox8-deficient lymphoma cells, compared to that in control shRen lymphoma cells." (PMID 36750552, 2023).